COX6A1 (cytochrome c oxidase subunit 6A1)
Description:
Component of the cytochrome c oxidase, the last enzyme in the mitochondrial electron transport chain which drives oxidative phosphorylation. The respiratory chain contains 3 multisubunit complexes succinate dehydrogenase (complex II, CII), ubiquinol-cytochrome c oxidoreductase (cytochrome b-c1 complex, complex III, CIII) and cytochrome c oxidase (complex IV, CIV), that cooperate to transfer electrons derived from NADH and succinate to molecular oxygen, creating an electrochemical gradient over the inner membrane that drives transmembrane transport and the ATP synthase. Cytochrome c oxidase is the component of the respiratory chain that catalyzes the reduction of oxygen to water. Electrons originating from reduced cytochrome c in the intermembrane space (IMS) are transferred via the dinuclear copper A center (CU(A)) of subunit 2 and heme A of subunit 1 to the active site in subunit 1, a binuclear center (BNC) formed by heme A3 and copper B (CU(B)). The BNC reduces molecular oxygen to 2 water molecules unsing 4 electrons from cytochrome c in the IMS and 4 protons from the mitochondrial matrix.
Synonyms: COX6AL; CMTRID; COX6A
Tractability: Small molecule: a structure with a bound ligand is known. Antibody: UniProt predicts a signal peptide or a membrane-spanning region. PROTAC: ubiquitination databases record sites on it.
Gene: Protein-coding gene on chromosome 12 (120,438,090 to 120,440,742, forward strand). Ensembl gene ENSG00000111775.
Subcellular location: Mitochondrion inner membrane
Subcellular location (Human Protein Atlas): Mitochondria; Principal piece
Pathways (Reactome):
Metabolism: Complex IV assembly; Respiratory electron transport
Cellular responses to stimuli: Cytoprotection by HMOX1
Gene Ontology:
Molecular function: protein binding; enzyme regulator activity
Biological process: cellular respiration; generation of precursor metabolites and energy; mitochondrial electron transport, cytochrome c to oxygen; oxidative phosphorylation
Cellular component: mitochondrial inner membrane; mitochondrial membrane; mitochondrion; respiratory chain complex IV
Genetic constraint (gnomAD): Loss-of-function variants: 6 observed, 8.7 expected, observed/expected ratio (o/e) 0.69, 90% interval 0.38 to 1.36. That is too few expected variants to judge how well the gene tolerates losing a copy. Missense variants: 126 observed, 118.19 expected, observed/expected ratio (o/e) 1.07, 90% interval 0.92 to 1.24. Synonymous variants: 64 observed, 50.38 expected, observed/expected ratio (o/e) 1.27, 90% interval 1.04 to 1.56.
Gene-disease validity (ClinGen):
ClinGen rates the evidence that COX6A1 causes each of these diseases.
mitochondrial disease (autosomal recessive): Strong.
Homologues: Orthologues: chimpanzee COX6A1 (100% identical), macaque COX6A1 (95% identical), guinea pig COX6A1 (86% identical), mouse Cox6a1 (83% identical), pig COX6A1 (83% identical), rat Cox6a1 (83% identical), tropical clawed frog cox6a2 (60% identical), zebrafish cox6a2 (54% identical), Drosophila melanogaster COX6AL (39% identical), Drosophila melanogaster COX6AL2 (37% identical), Caenorhabditis elegans cox-6A (35% identical). Paralogues in human: COX6A2 (55% identical).
Diseases named in the same sentence as COX6A1 in open-access papers:
COX6A1 is named in the same sentence as 23 diseases in open-access papers, as found by Europe PMC text mining. Sharing a sentence is not in itself a finding about the gene and the disease. The quoted sentences say what the papers report.
Charcot-Marie-Tooth (CMT) disease (1 paper, 2019). "Mutations in COX6A1 and COX10 are associated with Charcot-Marie-Tooth (CMT) disease and mitochondrial disorders." (PMID 31834878, 2019).
Huntington disease (1 paper, 2021). Huntington disease (HD) is a rare neurodegenerative disorder of the central nervous system characterized by unwanted choreatic movements, behavioral and psychiatric disturbances and dementia. "Interestingly, several mitochondrial proteins involved in AD, PD and Huntington's disease were only significantly changed in the chronic low dose group, such as ATP synthase subunit epsilon (P56382), Cytochrome c oxidase subunit 7C (P17665), Cytochrome c oxidase subunit 6A1 (P43024)." (PMID 34197336, 2021).
Hypertension (1 paper, 2022). The presence of chronic increased pressure in the systemic arterial system. "Here, in the myocardium of the hypertension-induced HFpEF, we also observed the increased expression of PGC-1a after CANA treatment, which was consistent with the increased expression of the mitochondrial membrane respiratory chain component protein subunit Ndufb4, COX2, Cox4i1, Cox5b, and Cox6a1." (PMID 35370704, 2022).
liver dysfunction (1 paper, 2024). "COX6A1-deficient mice are highly likely to develop liver dysfunction." (PMID 39625960, 2024).
lung adenocarcinoma (1 paper, 2025). A carcinoma that arises from the lung and is characterized by the presence of malignant glandular epithelial cells. "Analysis of multiple lung adenocarcinoma datasets revealed a significant correlation between COX6A1 expression and the expression of CAF activation-related cytokines." (PMID 40331946, 2025). "CCK8 assays revealed that silencing COX6A1 significantly inhibited the proliferation of the lung adenocarcinoma cell lines A549 and H1299." (PMID 40331946, 2025).
lung carcinoma (1 paper, 2025). "This appears to be contrary to the high expression of COX6A1 in lung cancer, prompting us to further investigate this issue through rigorous experiments." (PMID 40331946, 2025). "Further in vitro studies were conducted to investigate the effect of COX6A1 overexpression in lung cancer cells on the infiltration of CAFs." (PMID 40331946, 2025). "Our in vitro experiments demonstrated that COX6A1 knockdown in lung cancer cells led to the upregulation of TGFB2, CXCL12, and FGF2." (PMID 40331946, 2025). "We conducted further in vitro studies to investigate the impact of COX6A1 knockdown on CAF infiltration in lung cancer cells." (PMID 40331946, 2025). "To validate this finding, we used qPCR to measure the expression levels of several CAF-related cytokines in lung cancer cells with COX6A1 knockdown." (PMID 40331946, 2025). "Additionally, further co-culture studies of lung cancer cells and fibroblasts revealed that COX6A1 knockdown promotes the expression of CAF-related cytokines, enhancing CAF infiltration." (PMID 40331946, 2025). "In vitro experiments confirmed COX6A1’s role in lung cancer cells." (PMID 40331946, 2025). "Additionally, ELISA further confirmed that the expression level of CXCL12 in the culture supernatant of COX6A1-knockdown lung cancer cells was significantly reduced." (PMID 40331946, 2025). "To investigate the specific mechanism by which COX6A1 affects CAF infiltration, we established a co-culture system of lung cancer cells and human embryonic lung cells WI-38." (PMID 40331946, 2025).
viral infection (1 paper, 2016). "Therefore, we concluded that COX6A1 was not a key player in the outcome of the viral infection." (PMID 27655697, 2016).
cancer (3 papers, 2024 to 2025). A tumor composed of atypical neoplastic, often pleomorphic cells that invade other tissues. "Moreover, inhibition of PLK1 by BI2536 could reduce gefitinib‐induced hepatotoxicity by restoring COX6A1 expression without impairing the anti‐cancer activity of gefitinib." (PMID 39994841, 2025).
tumor (2 papers, 2025). "Moreover, COX6A1 was also associated with immune cell infiltration scores for various cell types, including mast cells, tumor-associated fibroblasts, and hematopoietic stem cells, as were matrix scores, immune microenvironment scores, and immune scores." (PMID 40331946, 2025). "Overall, this study provides a foundation for personalized treatment of LUAD and highlights COX6A1 as a promising therapeutic target within the tumor immune microenvironment, guiding future clinical research." (PMID 40331946, 2025). "In our analysis of the TCGA LUAD dataset, we identified COX6A1 as a key gene that promotes tumor progression within our predictive model." (PMID 40331946, 2025). "COX6A1 knockdown inhibited tumor cell migration and proliferation while promoting cellular senescence—a state where cells cease to divide after stress, accompanied by metabolic and gene expression changes." (PMID 40331946, 2025). "Our study deepens the understanding of the role of CAFs in tumor progression and highlights the importance of COX6A1 in the tumor immune microenvironment, revealing its clinical application prospects as a potential therapeutic target." (PMID 40331946, 2025). "Further validation across multiple datasets revealed that COX6A1 expression was significantly higher in tumor tissues than in normal tissues." (PMID 40331946, 2025). "Additionally, COX6A1 expression was significantly positively correlated with tumor stemness, further suggesting its role in maintaining aggressive tumor characteristics." (PMID 40331946, 2025). "Knockdown of COX6A1 significantly upregulated senescence-associated genes, such as CDKN1A and CDKN2A, indicating that COX6A1 may inhibit tumor progression by inducing senescence." (PMID 40331946, 2025). "In particular, we found that the upregulation of COX6A1 in LUAD is closely associated with immune cell infiltration, immune escape, and biological features such as tumor cell migration and senescence, suggesting its important regulatory role in the tumor microenvironment." (PMID 40331946, 2025). "Further in vitro experiments demonstrated that COX6A1 regulates LUAD cell migration, proliferation, and senescence, suggesting its role in tumor immune evasion." (PMID 40331946, 2025). "We further investigated contexts of these spMOCA’s hub genes, where we identified specific prognostic genes serves as hub genes in the same tumor type, for example, WIPF2 and CASC3 for BRCA, COX6A1 and PRAP1 for CRC, E2F1 and AKR1C3 for LUSC, and TSPAN3 and SLC4A11 for OVCA." (PMID 41370198, 2025).
infection (1 paper, 2024). The state of being infected such as from the introduction of a foreign agent such as serum, vaccine, antigenic substance or organism. "In the current study, we noted that UGT1A1, ALB, and COX6A1 in the late-infection-stage PPI are associated with liver homeostasis." (PMID 39625960, 2024).
mitochondrial disease (1 paper, 2024). "Interestingly, the cytochrome c oxidase subunit 6A1 (COX6A1) was downregulated in the CIV but upregulated in the CI defect groups, suggesting that COX6A1 might help distinguish between these 2 mitochondrial disease groups." (PMID 39288270, 2024).
neurodegenerative disease (1 paper, 2019). A disorder of the central nervous system characterized by gradual and progressive loss of neural tissue and neurologic function. "Cox6a1 is also involved in stress-induced apoptosis and neurodegenerative diseases in organs with a high-energy demand." (PMID 31073529, 2019).
peripheral neuropathy (1 paper, 2017). A disorder affecting the peripheral nervous system. "For example, COX6A1, a mitochondrial-associated gene in which mutations are causative of peripheral neuropathy, was found to be down-regulated in both Cnp-KO mice and in the hippocampus of AD patients." (PMID 29110684, 2017).
COX6A1 also shares sentences with these, for which no sentence is quoted: Alzheimer disease (2 papers); cardiac hypertrophy (2); breast carcinoma (1); diabetes (1); fatty liver (1); glioblastoma (1); Hypercholesterolemia (1); hypothyroidism (1); lipid metabolism disorders (1); Sepsis (1).